RABGGTB (Rab geranylgeranyltransferase subunit beta)
Description:
Catalyzes the transfer of a geranylgeranyl moiety from geranylgeranyl diphosphate to both cysteines of Rab proteins with the C-terminal sequence -XXCC, -XCXC and -CCXX, such as RAB1A, RAB3A, RAB5A and RAB7A. Catalytic subunit of the geranylgeranyl transferase type 3 (GGTase-3) complex. The GGTase-3 complex geranylgeranylates and targets FBXL2 to the cellular membranes, where FBXL2 forms part of the E3 ubiquitin-protein ligase complex SCF(FBXL2) that mediates the degradation of membrane-anchored proteins. The GGTase-3 complex geranylgeranylates Golgi v-SNARE protein YKT6 at 'Cys-194' and this prenylation is required for Golgi SNARE complex assembly.
Synonyms: GGTB
Tractability: Small molecule: a structure with a bound ligand is known; a high-quality ligand is known. Antibody: its Gene Ontology location is reachable by antibodies, with high confidence. PROTAC: ubiquitination databases record sites on it; its protein half-life has been measured; a small molecule that binds it is known.
Gene: Protein-coding gene on chromosome 1 (75,786,188 to 75,795,086, forward strand). Ensembl gene ENSG00000137955.
Subcellular location (Human Protein Atlas): Vesicles
Pathways (Reactome):
Metabolism of proteins: RAB geranylgeranylation
Gene Ontology:
Molecular function: protein binding; protein geranylgeranyltransferase activity; Rab geranylgeranyltransferase activity; small GTPase binding; zinc ion binding; catalytic activity; protein prenyltransferase activity
Biological process: endoplasmic reticulum to Golgi vesicle-mediated transport; protein geranylgeranylation; protein modification process; visual perception
Cellular component: cytosol; plasma membrane; Rab-protein geranylgeranyltransferase complex; cytoplasm
Genetic constraint (gnomAD): Loss-of-function variants: 19 observed, 40.51 expected, observed/expected ratio (o/e) 0.47, 90% interval 0.33 to 0.69. The upper end of that interval is the gene's LOEUF score, 0.69, which puts it in group 2 of 6, group 1 being the genes least tolerant of losing a copy. Missense variants: 282 observed, 395.38 expected, observed/expected ratio (o/e) 0.71, 90% interval 0.65 to 0.79. Synonymous variants: 122 observed, 137.56 expected, observed/expected ratio (o/e) 0.89, 90% interval 0.76 to 1.03.
Homologues: Orthologues: chimpanzee RABGGTB (100% identical), macaque RABGGTB (100% identical), dog RABGGTB (98% identical), guinea pig RABGGTB (97% identical), mouse Rabggtb (96% identical), rabbit RABGGTB (95% identical), rat Rabggtb (95% identical), zebrafish rabggtb (88% identical), Drosophila melanogaster RabGGTb (63% identical), Caenorhabditis elegans ggtb-1 (54% identical). Paralogues in human: FNTB (31% identical), PGGT1B (29% identical).
Diseases named in the same sentence as RABGGTB in open-access papers:
RABGGTB is named in the same sentence as 6 diseases in open-access papers, as found by Europe PMC text mining. Sharing a sentence is not in itself a finding about the gene and the disease. The quoted sentences say what the papers report.
multiple sclerosis (2 papers, 2023 to 2024). A progressive autoimmune disorder affecting the central nervous system resulting in demyelination. "The RABGGTB was significantly downregulated in the peripheral blood from patients with multiple sclerosis compared with healthy subjects, whereas high RABGGTB expression has been reported in tumor-associated disease." (PMID 39224887, 2024).
schizophrenia (2 papers, 2020 to 2025). A major psychotic disorder characterized by abnormalities in the perception or expression of reality. "To test this, we assayed protein expression of the five prenyltransferase subunits (FNTA, FNTB, PGGT1B, RABGGTA, and RABGGTB) in postmortem dorsolateral prefrontal cortex from patients with schizophrenia and paired comparison subjects (n = 13 pairs)." (PMID 32066669, 2020). "Accordingly, we assayed protein expression of the prenyltransferases subunits FNTA, FNTB, PGGT1B, RABGGTA, and RABGGTB in DLPFC from schizophrenia and matched comparison subjects." (PMID 32066669, 2020). "In addition, an increased gene expression level of RABGGTB has been reported in the postmortem prefrontal cortex of individuals with schizophrenia compared with healthy controls." (PMID 40272067, 2025). "We found decreased levels of FNTA (14%), PGGT1B (13%), and RABGGTB (8%) in schizophrenia." (PMID 32066669, 2020). "In summary, we found decreased protein expression of the prenyltransferase subunits FNTA, PGGT1B, and RABGGTB in schizophrenia DLPFC as well as evidence from a bioinformatic analysis of differential gene expression of prenylation-associated genes across multiple brain regions and cortical layers." (PMID 32066669, 2020). "We found protein expression of FNTA, PGGT1B, and RABGGTB prenyltransferase subunits decreased in schizophrenia DLPFC relative to paired comparison subjects, changes not likely due to chronic antipsychotic treatment." (PMID 32066669, 2020).
amyotrophic lateral sclerosis (1 paper, 2024). Amyotrophic lateral sclerosis (ALS) is a neurodegenerative disease characterized by progressive muscular paralysis reflecting degeneration of motor neurons in the primary motor cortex, corticospinal tracts, brainstem and spinal cord. "Geranylgeranyltransferase Subunit Beta (RABGGTB) was expressed at higher levels in patients with Amyotrophic lateral sclerosis (ALS) compared with healthy controls." (PMID 39224887, 2024).
infection (1 paper, 2023). The state of being infected such as from the introduction of a foreign agent such as serum, vaccine, antigenic substance or organism. "Taken together, these results showed that intrathecal injection of AAV9-GFP+ and AAV9-RabGGTB-GFP+ resulted in massive infection in lumbar regions of spinal cord, and highly efficient overexpression of RabGGTB was obtained in the neurons of spinal cord." (PMID 36967828, 2023).
tumor (1 paper, 2024). "The outcomes of the Kruskal–Wallis test unveiled a significant correlation between high expression levels of C1orf216 and EEF1E1 (p < 0.05), high expression of SRPRB (p < 0.01), high expression of RABGGTB (p < 0.001), and larger tumor size within the HCC cohort." (PMID 38972883, 2024).
RABGGTB also shares sentences with these, for which no sentence is quoted: cancer (1 paper).